PCSK7 (proprotein convertase subtilisin/kexin type 7)
Description:
Serine endoprotease that processes various proproteins by cleavage at paired basic amino acids, recognizing the RXXX[KR]R consensus motif. Likely functions in the constitutive secretory pathway.
Synonyms: PC7; PC8; LPC; SPC7
Tractability: Small molecule: a high-quality ligand is known. Antibody: UniProt predicts a signal peptide or a membrane-spanning region. PROTAC: ubiquitination databases record sites on it; a small molecule that binds it is known.
Target class: Enzyme; Serine protease S8B subfamily; Serine protease SB clan; Protease; Serine protease
Gene: Protein-coding gene on chromosome 11 (117,204,337 to 117,232,528, reverse strand). Ensembl gene ENSG00000160613.
Subcellular location: Golgi apparatus, trans-Golgi network membrane
Pathways (Reactome):
Cell-Cell communication: Regulation of CDH1 posttranslational processing and trafficking to plasma membrane
Gene Ontology:
Molecular function: peptidase activity; protein binding; serine-type endopeptidase activity; serine-type peptidase activity
Biological process: protein processing; peptide hormone processing; proteolysis
Cellular component: Golgi membrane; trans-Golgi network; cytoplasm; endomembrane system; Golgi apparatus
Genetic constraint (gnomAD): Loss-of-function variants: 29 observed, 44.88 expected, observed/expected ratio (o/e) 0.65, 90% interval 0.48 to 0.88. The upper end of that interval is the gene's LOEUF score, 0.88, which puts it in group 3 of 6, group 1 being the genes least tolerant of losing a copy. Missense variants: 541 observed, 693.28 expected, observed/expected ratio (o/e) 0.78, 90% interval 0.73 to 0.84. Synonymous variants: 240 observed, 267.84 expected, observed/expected ratio (o/e) 0.9, 90% interval 0.81 to 1.
Homologues: Orthologues: macaque PCSK7 (98% identical), chimpanzee PCSK7 (95% identical), dog PCSK7 (91% identical), pig PCSK7 (91% identical), guinea pig PCSK7 (89% identical), rabbit PCSK7 (88% identical), rat Pcsk7 (87% identical), mouse Pcsk7 (86% identical), tropical clawed frog pcsk7 (64% identical), zebrafish pcsk7 (56% identical). Paralogues in human: PCSK5 (36% identical), PCSK6 (35% identical), FURIN (32% identical), PCSK1 (31% identical), PCSK4 (31% identical), PCSK2 (29% identical), MBTPS1 (17% identical), TPP2 (14% identical), PCSK9 (13% identical).
Diseases named in the same sentence as PCSK7 in open-access papers:
PCSK7 is named in the same sentence as 38 diseases in open-access papers, as found by Europe PMC text mining. Sharing a sentence is not in itself a finding about the gene and the disease. The quoted sentences say what the papers report.
dyslipidemia (5 papers, 2020 to 2025). "The SNP is a non-coding exonic variant located in PCSK7, a gene whose perturbations have been linked to dyslipidemia." (PMID 38384714, 2024). "Proprotein convertase subtilisin/kexin type 7 (PCSK7) encodes Pcsk7 as a transmembrane protease, whose single-nucleotide variation (rs236918) is linked with dyslipidemia and liver damage in NAFLD patients." (PMID 38665220, 2024). "PCSK7 has been involved in lowering ApoA-V levels and recently a genetic variant in PCSK7 was associated with dyslipidemia and NAFLD." (PMID 36188622, 2022). "More recently a PCSK7 variant has been shown to lead to increased intracellular PCSK7 expression and secretion from hepatocytes, potentially linking dyslipidemia with a tendency to more severe liver damage in high risk individuals." (PMID 32759223, 2020). "Moreover, genetic variations, such as mutations in the PCSK7 gene, have been associated with dyslipidemia and more severe liver disease in NAFLD." (PMID 40290661, 2025).
acute coronary syndrome (3 papers, 2021 to 2023). Signs and symptoms related to acute ischemia of the myocardium secondary to coronary artery disease. "Increased PCSK7 expression in carotid plaques and in patients with previous myocardial infarction is a novel finding requiring further studies considering recent evidence linking PCSK7 variants to acute coronary syndrome." (PMID 36188622, 2022). "The association of three genetic variants of PCSK7 with HDL-C and acute coronary syndrome has also been recently published." (PMID 37944753, 2023).
breast carcinoma (3 papers, 2020 to 2025). "In accord, breast cancer patients’ data sets show that high CASC4 and PCSK7 expression levels predict a significantly worse prognosis compared to high CASC4 but low PCSK7 levels." (PMID 32820145, 2020). "Additionally, in the context of tumors, PCSK7 and Furin by cleaving CASC4 (a protein that maintains cell skeletal integrity) generate oncogenic N-terminal fragments that disrupt the cell skeleton, thereby affecting the malignant phenotypes such as migration and invasion in breast cancer cells." (PMID 40381082, 2025).
liver disease (3 papers, 2021 to 2025). "Recent studies have associated three novel SNPs [PCSK7 nearGene-3 rs508487 T/C, PCSK7 intron 6 rs236911 C/A, and PCSK7 intron 9 rs236918 C/G] with an over-expression of the PCSK7 and hypertriglyceridemia, as well as with the risk of developing atherosclerosis and liver disease." (PMID 34207761, 2021). "As far as we know, the precise mechanism by which PCSK7 decreases HDL-C and/or increases triglyceride levels in adverse events such as ACS, hypertriglyceridemia, and liver disease remains to be elucidated." (PMID 34207761, 2021).
atherosclerosis (2 papers, 2021 to 2022). A disease characterized by the build-up of fatty material and calcium deposition in the arterial wall resulting in partial or complete occlusion of the arterial lumen. "In atherosclerosis, we found that the expression of FURIN, PCSK5 and MBTPS1 was significantly lower in carotid plaques vs. normal artery controls, while PCSK6 and PCSK7 were increased." (PMID 36188622, 2022). "Our study also identified specific atherosclerosis-related transcription factors KLF4, KLF11 and BCLAF1 upstream from FURIN, PCSK6 or PCSK7." (PMID 36188622, 2022).
Cirrhosis (2 papers, 2017 to 2022). A chronic disorder of the liver in which liver tissue becomes scarred and is partially replaced by regenerative nodules and fibrotic tissue resulting in loss of liver function. "Cirrhosis develops in <10% of individuals homozygous for the C282Y variant in the homeostatic iron regulator (HFE) gene, where a gain-of-function variant of PCSK7 (rs236918) is associated with an increased risk of cirrhosis in this patient population." (PMID 35888711, 2022).
coronary artery disease (2 papers, 2021 to 2022). "SNPs in PCSK7 associated specifically with triglycerides (TG), while SNPs in PCSK9 strongly associated with LDL, cholesterol levels, and coronary artery disease (CAD)." (PMID 36188622, 2022).
Hepatic steatosis (2 papers, 2021 to 2022). Steatosis is a term used to denote lipid accumulation within hepatocytes. "Although, PCSK9 and PCSK7 can theoretically be associated with hepatic steatosis there is few clinical studies in this regard." (PMID 34876018, 2021). "This information may lead to novel approaches to silence PCSK7 expression to mitigate the development of fatty liver disease and its associated sequelae." (PMID 35888711, 2022). "We conducted this study to explore the association between genetic variations in TM6SF2 rs58542926, PCSK9 rs505151 and PCSK7 rs2277287 and hepatic steatosis in liver transplant recipients." (PMID 34876018, 2021). "Variations in PCSK7 rs2277287 gene was associated neither with presence nor degree of hepatic steatosis in liver transplant recipients." (PMID 34876018, 2021). "Our results support a regulatory role of these miRNAs on PCSK7 expression and function and open the way to assess their roles in the regulation of PC7 activity in vivo in the development of hepatic steatosis." (PMID 35888711, 2022). "The role of PCSK7 rs2277287 gene in hepatic steatosis has not been previously investigated." (PMID 34876018, 2021).
iron overload (2 papers, 2022 to 2025). "We found recurrent p.K689R variant in UBE2O and a high frequency of mutations in PCSK7 in primary iron overload patients." (PMID 35668470, 2022). "Our study revealed that HAMP mRNA was decreased in PCSK7-knockdown HCC cells, further indicating that PCSK7 may be a candidate gene or modifier gene causing iron overload involved in HH." (PMID 35668470, 2022). "Whole exome sequencing of 9 cases with unexplained primary iron overload identified 42 missense variants in 40 genes associated with iron metabolism pathway genes such as UBE2O p.K689R and PCSK7 p.R711W." (PMID 35668470, 2022). "We also identified high frequency of PCSK7 variations in patients with primary iron overload." (PMID 35668470, 2022). "In the present study, we firstly identified novel mutations by NGWES in a small number of patients with unexplained primary iron overload, then we screened for the mutations in the representative newly identified genes, UBE2O and PCSK7, in a larger cohort of primary iron overload patients." (PMID 35668470, 2022).
metabolic dysfunction-associated steatotic liver disease (2 papers, 2025). Metabolic dysfunction-associated steatotic liver disease (MASLD, formerly known as nonalcoholic fatty liver disease or NAFLD) is a type of liver disease that is not caused by alcohol. "In a mouse model, silencing Pcsk7 expression in hepatocytes through hepatocyte-specific N-acetylgalactosamine (GalNac) modified antisense oligonucleotides (ASOs) significantly improved the non-alcoholic fatty liver disease(NAFLD) phenotype." (PMID 40381082, 2025).
aneurysm (1 paper, 2022). Bulging or ballooning in an area of an artery secondary to arterial wall weakening. "In addition, the decreased expression and lack of co-localization of PCSK7 in aneurysm tissues may be explained by the characteristic loss of SMCs through apoptosis." (PMID 36188622, 2022).
colorectal cancer (1 paper, 2025). A primary or metastatic malignant neoplasm that affects the colon or rectum. "Future research needs to further explore the specific mechanisms of PCSK7 in colorectal cancer and how to prevent or treat CRC by modulating PCSK7 activity." (PMID 40381082, 2025). "We discovered that 428 DEGs had a causal association with colorectal cancer through eQTL, of which 38 genes met the FDR statistical standards, and four of these genes (CTSF, PCSK7, LYZ, LMAN2L) also had causal associations through pQTL." (PMID 40381082, 2025). "By integrating single-cell data, transcriptomic data, proteomic data and GWAS data for MR analysis, we identified CTSF, PCSK7, LYZ, LMAN2L as potential targets for colorectal cancer." (PMID 40381082, 2025). "This study identified CTSF, PCSK7, LYZ, and LMAN2L as critical regulatory genes in colorectal cancer, demonstrating their multifaceted clinical potential in diagnosis, therapeutic intervention, and prognostic evaluation." (PMID 40381082, 2025).
Ehlers-Danlos syndrome (1 paper, 2022). The Ehlers–Danlos syndromes (EDS) are a clinically and genetically heterogeneous group of heritable connective tissue disorders (HCTDs) characterized by joint hypermobility, skin hyperextensibility, and tissue fragility. "RNF214 is a protein-coding gene linked to disorders including Ehlers-Danlos syndrome, a group of heritable tissue disorders.The PCSK7 gene encodes enzymes that process protein and peptide precursors trafficking." (PMID 36137169, 2022).
end-stage renal disease (1 paper, 2022). "Two of these proprotein convertases have been previously associated with kidney disease: specifically, in the kidney, a high-salt diet induces the PCSK6-corin-ANP-AQP2/β-ENaC pathway suggesting the importance of PCSK6 in renal failure, whereas PCSK7 is linked to end-stage renal disease (ESRD)." (PMID 35045102, 2022).
heart failure (1 paper, 2021). Inability of the heart to pump blood at an adequate rate to meet tissue metabolic requirements. "From the 4 predicted proprotein convertases, three PCSK6 PSCK5 and PCSK7, have been previously associated with heart failure, to our knowledge." (PMID 34376786, 2021).
hepatocellular carcinoma (1 paper, 2022). A malignant tumor that arises from hepatocytes. "In the hepatocellular carcinoma cell line Huh7, it was previously demonstrated that TfR1 could be proteolytically cleaved by PC7, encoded by PCSK7, but not by TMPRSS6." (PMID 36044454, 2022).
hereditary hemochromatosis (1 paper, 2022). An inherited metabolic disorder characterized by iron accumulation in the tissues. "Our present Western blot analysis demonstrated that PCSK7 inhibition by miR-125a-5p reduced the shedding of hTfR1, suggesting that miR-125a-5p could reduce the enzymatic function of PC7 and inhibit the shedding of hTfR1 and could find applications in the treatment of hereditary hemochromatosis." (PMID 35888711, 2022).
hyperlipidemia (1 paper, 2023). "In this study, within the EV HFD group, we were able to show alteration in methylation of the PCSK7 gene, which has been implicated in hyperlipidemia." (PMID 37982029, 2023).
hypertriglyceridemia (1 paper, 2021). A laboratory test result indicating elevated triglyceride concentration in the blood. "Genome-wide association studies (GWAS) have shown that some single nucleotide polymorphisms (SNPs) of the PCSK7 gene are associated with hypertriglyceridemia, with large effects on HDL-C and/or triglyceride levels." (PMID 34207761, 2021).
liver fibrosis (1 paper, 2020). "It is noteworthy that PCSK7 missense variants identified in GWAS studies are associated with liver fibrosis." (PMID 32759223, 2020).
triple-negative breast carcinoma (1 paper, 2020). An invasive breast carcinoma which is negative for expression of estrogen receptor (ER), progesterone receptor (PR), and human epidermal growth factor receptor 2 (HER2). "Second, we analyzed the expression levels of CASC4, PCSK7, and Furin mRNA levels in MCF10a (human non-cancerous breast epithelial cell line) versus MDA-MB-231 (highly metastatic triple-negative breast cancer cell line) cells by qPCR." (PMID 32820145, 2020).
cancer (4 papers, 2014 to 2022). A tumor composed of atypical neoplastic, often pleomorphic cells that invade other tissues. "However, further investigations are needed to specify which miRNAs significantly regulate the expression of PCSK7 in different liver pathologies and/or cancers." (PMID 35888711, 2022).
cardiovascular disease (4 papers, 2016 to 2022). "The 4th gene hit in “IN”-Pcsk7 (proprotein convertase subtilisin/kexin type 7) was also associated with cardiovascular disease phenotypes." (PMID 36013195, 2022). "Recent research of cardiovascular Disease (CVD) network using 1512 SNPs associated with 21 traits in genome-wide association showed PCSK7 connected closely to the incidence of CVD." (PMID 30532766, 2018).
PCSK7 also shares sentences with these, for which no sentence is quoted: colon cancer (2 papers); diabetes (2); hepatic cancer (2); lung carcinoma (2); tumor (2); hemochromatosis (1); Hypertension (1); Insulin resistance (1); iron disorders (1); kidney disease (1); leukemia (1); liver cirrhosis (1); myocardial infarction (1); renal failure (1); steatosis (1).